THBS1 (thrombospondin 1)
Diseases named in the same sentence as THBS1 in open-access papers (continued):
Sharing a sentence is not in itself a finding about the gene and the disease.
breast carcinoma (continued). "In support of this hypothesis, in breast cancer, THBS2 was found to promote cell invasion by activating the PI3K/AKT signaling pathway, while THBS1-induced breast cancer cell invasion occurs by the YAP/FAK and transforming growth factor (TGF)-beta/Smad3 axes." (PMID 38339060, 2024). "In breast cancer, THBS1 promotes cancer cell adhesion and migration by engaging the α3β1 integrin." (PMID 38339060, 2024). "Mature endothelial cell–derived thrombospondin-1 supports breast cancer dormancy." (PMID 38457510, 2024). "Strikingly, endothelial-derived thrombospondin-1 in the stable microvasculature induced sustained breast cancer cell quiescence, but this suppressive cue was lost in sprouting neovasculature, where ETC-derived active TGF-β1 and periostin promoted breast tumor growth." (PMID 36917178, 2023). "THBS1, on the other hand, plays a significant role in inflammation, angiogenesis, platelet aggregation, tumorigenesis, and tissue remodeling, and has been extensively studied in lymphoma, breast cancer, melanoma, and gastric cancer." (PMID 37122373, 2023). "Importantly, the top 4 genes induced by OSM in CAF-173 (SERPINB4, THBS1, RARRES1, and TNC) are associated with decreased overall survival in breast cancer patients." (PMID 35192545, 2022). "Parallel outcomes were observed that tRF‐3008a could suppress cells malignant activity silencing THBS1 in breast cancer." (PMID 35576497, 2022). "Moreover, using a model of THBS1 overexpressing breast cancer, recent work has shown that exosomes laden with THBS1 promote cancer cell migration via disruption of the endothelial barrier." (PMID 35257663, 2022). "In the luminal or HER2-enriched subtype of breast cancer, anti-HER2 trastuzumab and metronomic chemotherapy could also induce vascular normalization by upregulating the expression of thrombospondin-1 (THBS1) in breast cancer." (PMID 34294146, 2021). "Moreover, tRF-17 attenuated the THBS1-mediated TGF-β1/Smad3 signaling pathway in breast cancer cells." (PMID 33912465, 2021). "Furthermore, reduction of THBS1 expression also partially recovered the effects of tRF-17-79MP9PP inhibition on breast cancer cell viability, invasion and migration compared to that in the control group." (PMID 33912465, 2021). "tRF-17-79MP9PP targets THBS1 3′ UTR to attenuate breast cancer cell invasion and migration." (PMID 34537070, 2021). "On the other hand, THBS1 has been reported to promote human follicular thyroid carcinoma cell invasion through the upregulation of urokinase-dependent activity and metastasis to the lungs in a transgenic mouse model of breast cancer." (PMID 34268116, 2021). "Our interest in studying the role of the secreted protein thrombospondin-1 (TSP1, encoded by THBS1) in the tumor microenvironment arose from our observation that TSP1 expression decreased during malignant progression in melanoma and breast carcinoma cell lines." (PMID 33925464, 2021). "TMSB4X, SRSF6, and THBS1 displayed high connectivity degree values among the human protein–protein interaction networks according to the topological analysis, introducing these proteins as potential signatures in PBMCs of breast cancer patients." (PMID 32793473, 2020). "In addition, THBS1 has been shown to promote cell invasion of breast cancer, thyroid cancer, colon cancer and prostate cancer." (PMID 32894090, 2020). "Glycoproteins or short peptides derived from quiescence-inducing proteins such as the thrombospondin-1-inducing glycoprotein prosaposin have successfully induced systemic thrombospondin-1 to inhibit the metastatic outgrowth of prostate and breast cancer lung metastases." (PMID 33014869, 2020). "In nude mice experiments, transfection of THBS1 could slow the growth, metastasis, and angiogenesis of breast cancer." (PMID 32117788, 2019).
breast carcinoma (continued). "Subsequent analysis using a publicly-available dataset revealed that the coordinated low-expression of CD163 and CXCR4 with high expression of THBS1 in 161 breast cancer tissues identified patients with TNBC (basal) having a high risk of recurrence and poor survival rate." (PMID 30254632, 2018). "Here, we show that peroxisome proliferator-activated receptor (PPAR) δ regulates migration and invasion of human breast cancer cells via thrombospondin-1 (TSP-1) and its degrading protease, a disintegrin and metalloprotease domains with thrombospondin motifs 1 (ADAMTS1)." (PMID 29212212, 2017). "Thus, up-regulation of THBS1, TNC, FN, SPARC and α-SMA following neoadjuvant chemotherapy was associated with chemotherapy resistance in breast cancer patients." (PMID 27487140, 2016). "Four known biomarkers (CHEK2 in both plasma and urine, CDKN1B, PCNA, and THBS1) were identified as false positives (red) in our breast cancer list, and seven (KRAS, GDNF in both breastmilk and plasma, MYCL1 in both blood and serum, CD40LG, CGA, CTAG1A, ERCC6, and HRAS) in our lung cancer list." (PMID 25379168, 2014). "◊ Thrombospondin-1 facilitates breast cancer cell migration in vitro." (PMID 26273699, 2014). "Although THBS1 expression was inversely correlated with cell invasion in thyroid cancer in one study, other studies reported that THBS1 promotes cell invasion in breast cancer, thyroid cancer, colon cancer and prostate tumors." (PMID 25051363, 2014). "In addition, knock-out of THBS1 in an animal model of breast cancer led to growth of the primary tumor but a decrease in the number of metastases." (PMID 25051363, 2014). "Thrombospondin-1 (TSP1) was the first endogenous angiogenesis inhibitor to be identified and its loss is among the critical events in progression of multiple cancers including carcinomas of the breast and colon as well as skin cancers." (PMID 25526033, 2014). "Moreover, it has been proven that THBS1 overexpression results in resistance to DOXO-mediated apoptosis of breast cancer cells (type I collagen seems to be involved in this effect), whereas OPN overexpression results in resistance to CPH-dependent apoptosis of these cells." (PMID 35268340, 2022). "Therefore, we hypothesized that tRF-17-79MP9PP-mediated THBS1 inhibition may lead to the inactivation of TGF-β1/Smad3 signaling pathway in breast cancer cells." (PMID 33912465, 2021). "Therefore, we hypothesized that tRF-17-79MP9PP might contribute to breast cancer progression via the THBS1/TGF-β1/Smad3 pathway." (PMID 33912465, 2021). "The results suggest that tRF-17-79MP9PP may regulate TGF-β1 through THBS1 in breast cancer cells." (PMID 33912465, 2021). "In this context, the increase in THBS1 expression has been found to be associated with the enhancement of angiogenic properties in the gastric carcinoma model and more importantly, it has been reported to up-regulate the expression of MMP9 in breast cancer cells." (PMID 29748481, 2018). "Second, the TCGA BRCA dataset (n = 821) with PAM50 subtypes called by RNAseq was used to validate the differentially expression of COL2A1, COL11A1, COL6A1, COL6A2, THBS1 and LUM among four breast cancer molecular subytpes in an independent cohort." (PMID 40927672, 2025). "In breast cancer, YAP–TEAD directly activates the transcription of THBS1, which functions upstream of FAK." (PMID 40895190, 2025). "Disease-specific survival discrepancy was observed comparing breast cancer patients of the upper and lower quartile of the collagen family (COL2A1, COL11A1, COL6A1, COL6A2), THBS1 and LUM gene expression signature (log-rank test, P = 0.06)." (PMID 40927672, 2025). "Overexpression of tRF-17 can inhibit the invasion and migration of breast cancer cells by targeting and suppressing the THBS1 (Thrombospondin-1) mediated TGF-b1/Smad 3 signaling pathway." (PMID 38577588, 2024).
breast carcinoma (continued). "Worthy, the signature demonstrated to predict poor outcomes in breast cancer patients exhibiting high transcriptional levels of ITGA11, THBS1, FN1, EMP1, ITGA2, FYN, SPP1, and EMP2." (PMID 38937754, 2024). "Collectively, our findings suggest that Kaiso, CD47, SIPRA, and THBS1, gene signature is related to ER-negative basal-like tumors, which includes TNBC breast cancer patients." (PMID 37190208, 2023). "To determine the biological significance of Kaiso with the THBS1/CD47/SIRPA signaling axis, we first analyzed two datasets that contained gene expression from commonly utilized breast cancer cell lines." (PMID 37190208, 2023). "For example, PKHB1, a thrombospondin-1 peptide mimic, can induce DAMPs in breast cancer cell lines, and the supernatant of PKHB1-killed breast cancer cells can induce maturation of bone-marrow-derived DCs and elicit antitumor T cell responses." (PMID 35625834, 2022). "Tetrac induced the upregulation of gene expressions of both the antiangiogenic thrombospondin 1 (THBS1) and antiapoptotic XIAP in human breast cancer cells." (PMID 36005485, 2022). "For example, THBS1 (thrombospondin 1) activates focal adhesion kinase when transcriptionally activated by YAP1, which regulates breast cancer progression and metastasis, promoting tumor aggressiveness." (PMID 35407556, 2022). "PRMT6 was observed overexpressed in breast cancer MCF7 cell lines, while the levels of thrombospondin-1 (TSP-1), an effective natural inhibitor of angiogenesis, were highly up-regulated in PRMT6-overexpressing cells." (PMID 35311114, 2022). "Among these candidates, SERPINE1, LTBP1, and THBS1 are involved in TGF-beta receptor signaling, which was reported previously to be regulated by the BRCA gene and to induce “BRCAness” in breast cancer." (PMID 34064977, 2021). "In this case, downregulation of Cx43 in human breast cancer cell lines (MDA-MB-231 and Hs578T) was correlated with an increase of thrombospondin-1 and VEGF, two antiangiogenic molecules." (PMID 34830485, 2021). "once reported a new signal axis, YAP/THBS1/FAK, in the modulation of adhesion and invasiveness of breast cancer." (PMID 33912465, 2021). "Our data suggested that tRF-17-79MP9PP inhibits the THBS1-mediated TGF-β1/Smad3 pathway and the EMT related genes (MMP3, MMP-9 and N-cadherin) in breast cancer cells." (PMID 33912465, 2021). "However, it remains unclear whether THBS1 participates in breast cancer." (PMID 33912465, 2021). "Youden index analysis also showed that five proteins including S100A9, SRSF6, THBS1, CUL4A, and CANX can accurately diagnose breast cancer patients at the metastatic and primary stages from healthy individuals." (PMID 32793473, 2020). "The identified PBMC biomarkers (TMSB4X, HSPA4, S100A9, SRSF6, THBS1, CUL4A, and CANX) were significantly upregulated in the breast cancer patients at the metastatic stage compared to both the primary stage and healthy individuals (p < 0.001)." (PMID 32793473, 2020). "In summary, with this study, we have proven that YAP acts as an upstream regulator in focal adhesion dynamics and have discovered a YAP/THBS1/FAK signalling mechanism in the regulation of cell invasiveness and adhesion in breast cancer." (PMID 30055645, 2018). "In this research, we provide evidence from clinical specimens and breast cancer cell lines that YAP acts as a promoter of focal adhesion and tumour invasiveness via regulating the transcription of thrombospondin 1, leading to the phosphorylation of FAK." (PMID 30055645, 2018). "Another study using plasma showed that thrombospondin-1 (THBS1) and bromodomain and WD repeat-containing protein 3 (BRWD3) were overexpressed in breast cancer using mTRAQ and Western blot." (PMID 24550697, 2014). "To determine the effect of tumour cell-produced thrombospondin-1 in the regulation of the plasminogen/plasmin system and tumour cell invasion, we studied THBS-1 -transfected MDA-MB-435 breast cancer cells that overexpress thrombospondin-1." (PMID 10917542, 2000).
breast carcinoma (continued). "Additionally, breast cancer cell-secreted cathepsin C (CTSC) induces neutrophil production of ROS and NETs via the CTSC-PR3-IL-1β axis, leading to thrombospondin-1 (THBS1) degradation and reduced endothelial adhesion, ultimately facilitating lung metastasis." (PMID 40568594, 2025). "Thrombospondin-1 supports breast cancer dormancy even when delivered without endothelial cell coculture, strongly supporting a soluble signaling pathway." (PMID 38457510, 2024). "Mature vasculature highly expresses thrombospondin-1, which promotes breast cancer cell dormancy even in the absence of endothelial cells." (PMID 38457510, 2024). "Moreover, endothelial cells in the bone microenvironment can secrete angiogenesis inhibitors such as thrombospondin-1 (TSP1), which promote dormancy in disseminated breast cancer cells." (PMID 39605887, 2024). "In addition, THBS1, RARRES1, and TNC levels correlate with OSMR expression in breast cancer clinical samples." (PMID 35192545, 2022). "In addition, the YAP/thrombospondin 1 (THBS1)/FAK signaling axis was shown to contribute to the adhesion, migration and invasion of breast cancer cells." (PMID 33562737, 2021). "Finally, in silico analysis confirmed that a gene set consisting of S100A9, SRSF6, THBS1, CUL4A, and CANX were found to provide an insight for the identification of metastasis in breast cancer patients." (PMID 32793473, 2020). "Among the identified transcripts, downregulation of COL6A2, SERPINA1, CCBE1, TFPI2, THBS1 and COL8A1 have been shown to promote migration and invasion of malign breast cancer cells, aggravate metastatic spread and result in poor prognosis of breast cancer patients." (PMID 31848385, 2019). "Therefore, it appears that THBS1 and TNC promote breast cancer cell proliferation through differential mechanisms." (PMID 27487140, 2016). "The aim of this study was to determine the changes in a panel of stromal proteins within the tumor, including THBS1, TNC, FN, SPARC and α-SMA, following neoadjuvant chemotherapy in newly diagnosed breast cancer patients using immunohistochemistry (IHC) staining." (PMID 27487140, 2016). "THBS1 and TNC in the tumor microenvironment may bind to and activate integrin β1 on the surface of breast cancer cells to phosphorylate intracellular mTOR pathway." (PMID 27487140, 2016). "However, the role of THBS1 in breast cancer development has not been characterized." (PMID 33912465, 2021). "Finally, a gene set consisting of S100A9, SRSF6, THBS1, CUL4A, and CANX were introduced as potential candidate genes helpful in distinguishing metastatic from non-metastatic breast cancer patients." (PMID 32793473, 2020). "The expression of three of these genes (CD163, CXCR4, THBS1) was found to predict relapse-free survival in a large, publically-available transcriptomic dataset generated from the tumors of patients with TNBC, but not other breast cancer subtypes." (PMID 30254632, 2018).
melanoma (61 papers, 1995 to 2026). A malignant, usually aggressive tumor composed of atypical, neoplastic melanocytes. "THBS1 was also implicated in the development of several cancers, including breast, gastric, melanoma, and cervical cancers and glioblastoma." (PMID 34777463, 2021). "Another study also validated that increased expression of THBS1 is associated with an invasive and metastatic phenotype of melanoma, as part of a Slug-independent motility program that includes the melanoma-related VEGF/VEGFR-1 and FGF-2 pathways." (PMID 32894090, 2020). "This demonstrates the association between THBS1 expression and a de-differentiated phenotype in melanoma." (PMID 25051363, 2014). "Finally we demonstrate a striking association between the expression of THBS1 and drug resistance, not only to cytotoxic drugs, but also in melanoma cells resistant to BRAF inhibition." (PMID 25051363, 2014). "Thus, loss of THBS1 contributed to the restoration of E-cadherin levels and inhibition of invasion in melanoma cells." (PMID 25051363, 2014). "To assess whether THBS1 expression is associated with label-retaining cells (LRC) in melanoma, we isolated these cells by using CM-Dil dye, a membrane labeling carbocyanine dye that was distributed equally between daughter cells with each cell division." (PMID 25051363, 2014). "Furthermore, the loss of THBS1 inhibited in vivo motility of melanoma cells within the embryonic chicken neural tube." (PMID 25051363, 2014). "More strikingly, of the 150-proteins identified by the authors at melanoma-specific Thrombospondin-1 was in the top 5 of a subset of proteins that were predictive for metastatic progression of disease." (PMID 40654904, 2025). "Perturbation of macrophage migration inhibitory factor expression in mouse melanoma suppresses tumor formation by up-regulating Thrombospondin-1 (TSP-1)." (PMID 37744272, 2023). "Like THBS1, CYR61 has also been directly implicated in the promotion of melanoma metastasis by increasing cell invasion." (PMID 37835395, 2023). "There are also studies in which the species Salmonella choleraesuis performs the bactofection of a plasmid encoding thrombospondin-1 (TSP-1) or endostatin, that inhibited tumor growth and prolonged survival in murine melanoma and bladder tumor model." (PMID 36077761, 2022). "In melanoma, new markers are continuously exposed through bioinformatics technologies, and multiple markers including IL27, CXCL8, THBS1, and KIT have been identified to be associated with melanoma metastasis and treatment outcomes." (PMID 36438905, 2022). "By assessing the data for 60 cell lines at the National Cancer Institute (NCI-60), we found that THBS1 protein is present in extracellular vesicles derived from the breast, CNS (Central Nervous System), colon, kidney, lung, melanoma, and ovarian cancer cells." (PMID 34804159, 2021). "Promoter methylation of THBS1 gene has been studied in various malignancies, such as colorectal cancer, melanoma, and GC tissues." (PMID 34390026, 2021). "Aberrant THBS1 methylation was detected in gastric cardia adenocarcinoma, melanoma, colorectal cancer, and so on, which is believed to promote tumorigenesis through its effect on angiogenesis." (PMID 34390026, 2021). "Sensitivity of B16 melanomas in immune-competent mice to ablation by tumor irradiation was enhanced when either Thbs1 or Cd47 were disrupted in the tumor microenvironment." (PMID 33925464, 2021). "For example, we detected the presence of thrombospondin-1, which is involved in a melanoma epithelial-to-mesenchymal transition (EMT)-like process, or to protein FAM3C, and possibly related to EMT, tumor progression, and metastasis." (PMID 33467521, 2021). "Consistent with mRNA expression, we found that the expression of CXCL8 and THBS1 protein in metastatic melanoma was significantly higher than that of primary melanoma, while the expression level of KIT was lower." (PMID 32894090, 2020).